REN (renin)
Diseases named in the same sentence as REN in open-access papers (continued):
Sharing a sentence is not in itself a finding about the gene and the disease.
diabetic nephropathy (continued). "For instance, melatonin suppressed the renin-angiotensin system in the kidney in 5/6Nx models, inhibited fibroblast-myofibroblast trans-differentiation during renal fibrosis in unilateral ureteral obstruction mice, and mitigated oxidative stress in diabetic nephropathy rats." (PMID 34376166, 2021). "Angiotensin-I converting enzyme (ACE) is one of the key enzymes in the renin-angiotensin-aldosterone system (RAAS) and the insertion (I)/deletion (D) polymorphism of this gene has been studied extensively with renal and cardiovascular complications of diabetic nephropathy." (PMID 25587546, 2014). "Renin–angiotensin–aldosterone system (RAS) inhibitors and sodium-glucose cotransporter 2 (SGLT2) inhibitors are key treatments for diabetic kidney disease." (PMID 40660221, 2025). "Two studies addressed the role of renin–angiotensin–aldosterone system (RAAS)-related genes in CKD and diabetic nephropathy." (PMID 39857298, 2025). "Current treatments of diabetic nephropathy, including sodium‐glucose cotransporter 2 (SGLT‐2) inhibitors and renin‐angiotensin‐aldosterone system (RAAS) inhibitors, delay the progression of diabetic nephropathy and suppress protein O‐GlcNAcylation." (PMID 39279604, 2025). "Current treatments for diabetic nephropathy, such as sodium‐glucose cotransporter 2 (SGLT‐2) inhibitors and renin–angiotensin–aldosterone system (RAAS) inhibitors, delay disease progression, and suppress protein O‐GlcNAcylation." (PMID 39279604, 2025). "We investigated the effect of a single dose of liraglutide on diurnal blood pressure profile, natriuresis, hydration and serum concentration of renin, aldosterone and atrial natriuretic peptide (ANP) in diabetic kidney disease (DKD)." (PMID 38424466, 2024). "According to the treatment guidelines, a combination of ACEIs, ARBs, and direct renin inhibitors is not recommended due to the greater risk of hyperkalemia and hypotension and the lack of demonstrated benefit in cardiology trials and diabetic nephropathy trials." (PMID 36938155, 2023). "In patients with diabetic kidney disease (DKD), the renin-angiotensin-aldosterone (RAA) axis is upregulated, which results in many progressive kidney diseases." (PMID 36819350, 2023). "In patients with diabetic kidney disease (DKD), there are several trials confirming the benefit of SGLT2 inhibitors, in addition to renin–angiotensin system (RAS) blockade, in decreasing HF events." (PMID 37109553, 2023). "This may be due to the similar pathogenesis of DR and diabetic nephropathy, including hyperglycemia-induced oxidative stress, accumulation of glycation end products, increased reactive oxygen species, abnormal activation of protein kinase C, and abnormal renin-angiotensin system activation." (PMID 37181375, 2023). "The maladaptive activation of the renin–angiotensin system (RAS) increases glomerular capillary pressure, thus playing a fundamental role in the pathophysiology of diabetic nephropathy progression." (PMID 35884947, 2022). "For example, in transgenic rodents with an excessively activated renin-angiotensin-aldosterone system to induce HTN, there is an accelerated development of diabetic nephropathy." (PMID 34866402, 2022). "Although the significance of vitamin D deficiency in the development of diabetic nephropathy is not known well, several studies demonstrated the protective effect of this vitamin and its analogs on podocytes and their regulatory role in the renin-angiotensin-aldosterone system." (PMID 35787282, 2022). "Considering the benefits of direct renin inhibitors in terms of reducing UACR and albuminuria levels, further studies need to be continued in people with diabetic kidney disease." (PMID 36204481, 2022). "A range of in vitro, experimental and clinical intervention studies have implicated an important role for hyperglycaemia-induced activation of the renin-angiotensin system (RAS) in the development and progression of diabetic nephropathy (DN)." (PMID 24330074, 2014).
diabetic nephropathy (continued). "Here, we review the role of miRNA in regulating the renin-angiotensin system, AGE/RAGE signalling, and under conditions of oxidative stress in the context of diabetic nephropathy." (PMID 24575418, 2013). "Furthermore, miRNA exerts regulatory effects on the renin-angiotensin system, AGE/RAGE signaling, and oxidative stress in diabetic nephropathy." (PMID 38671903, 2024). "Thus, our study suggests that pharmacological inhibition of the β-adrenoceptor/renin/Ang pathway is beneficial to prevent the development of DPN, in addition to diabetic nephropathy and cardiomyopathy, in T2DM patients." (PMID 38200077, 2024). "Even when diabetic patients have normal to low levels of plasma renin activity, RAS inhibitors are still effective in reducing albuminuria; thus, supporting the role of the RAS in these compartments in the progression of diabetic nephropathy." (PMID 38203807, 2024). "Since renin–angiotensin system (RAS) inhibitors are thought to have both antihypertensive and renoprotective activity, they are currently recommended in Japan and elsewhere as a first-line therapy for hypertensive patients with diabetic nephropathy." (PMID 32616846, 2020). "Of note, the nonproteinuric diabetic kidney disease group was less prescribed renin-angiotensin system blockades (48%), compared to the proteinuric diabetic kidney disease group (69%)." (PMID 32236782, 2020). "PRR activation by binding (pro)renin may activate ERK1/2 signaling, resulting in the production of profibrotic factors in diabetic nephropathy, such as TGF-β1." (PMID 29056916, 2017). "High glucose has been demonstrated to induce angiotensinogen (AGT) synthesis in the renal proximal tubular cells (RPTCs) of rats, which may further activate the intrarenal renin-angiotensin system (RAS) and contribute to diabetic nephropathy." (PMID 29053707, 2017). "Although recent studies have proven that renin-angiotensin system (RAS) blockades retard the progression of diabetic nephropathy, the detailed mechanisms of their reno-protective effects on the development of diabetic nephropathy remain uncertain." (PMID 24284398, 2013). "Therefore, we believe that endogenous adrenomedullin counteracts the pathogenesis of diabetic nephropathy possibly through an antioxidative stress action via the suppression of NADPH oxidase and the renin-angiotensin system." (PMID 23957015, 2013). "Therefore, combination of metformin, silymarin and renin-angiotensin system inhibitors or angiotensin receptor blockers may have additive kidney protective property beyond controlling the blood sugar of metformin, to prevent or slowing the progression of diabetic nephropathy." (PMID 25340091, 2012). "Currently renin-angiotensin system blockade is the gold standard in diabetic nephropathy treatment that lead to slowing the renal impairment but not arrest or reverse of the disease." (PMID 25340102, 2012). "Some studies have indicated that genistein supplementation may help regulate blood pressure by affecting renin secretion and inhibiting cellular apoptosis through inhibition of SIRT1 gene expression in common kidney diseases (diabetic nephropathy, hypertensive kidney disease, and renal fibrosis)." (PMID 39770942, 2024). "Furthermore, it may suppress the renin-angiotensin-aldosterone system (RAAS), the main renal injury player in diabetic nephropathy." (PMID 35787282, 2022). "Direct renin inhibitors are not currently recommended for use in diabetic nephropathy." (PMID 34979961, 2022). "However, apart from renin-angiotensin-aldosterone blockers, there were few breakthroughs about treatment for diabetic nephropathy in recent years, beta-blockers and statins have not been shown to significantly improve the pathophysiology of diabetic nephropathy." (PMID 38365853, 2024).
diabetic nephropathy (continued). "Angiotensin II (AngII), a major component in the renin–angiotensin system (RAS), plays a pivotal role and is not only activated systemically in diabetic nephropathy, but also locally activated in each organ." (PMID 32977573, 2020).
Hyperkalemia (174 papers, 2009 to 2026). An abnormally increased potassium concentration in the blood. "In clinical practice, the up-titration of foundational GDMT, particularly renin–angiotensin system inhibitors and MRAs, is often hindered by concerns about drug-related worsening renal function and hyperkalemia, particularly in high-risk patients." (PMID 40869682, 2025). "In patients with hyporeninemic hypoaldosteronism, the risk of developing hyperkalemia increases due to the decrease in renin release due to damage to the juxtaglomerular apparatus and decrease in aldosterone release in the adrenal gland." (PMID 40747151, 2025). "Hyperkalemia is common in clinical practice and can be caused by medications used to treat cardiovascular diseases, particularly renin–angiotensin–aldosterone system inhibitors (RAASis)." (PMID 37775712, 2024). "Hyperkalemia can be caused by medications used to treat cardiovascular disease, particularly renin–angiotensin–aldosterone system inhibitors (RAASis)." (PMID 37775712, 2024). "Relative risks of CKD progression associated with hyperkalemia were similar within the subset of patients receiving renin-angiotensin-aldosterone system inhibitor, across CKD stages, and when alternative definitions of CKD progression were used." (PMID 39120948, 2024). "Another risk of hyperkalemia is the use of renin-angiotensin-aldosterone system inhibitors (RAASi) and/or mineralocorticoid receptor antagonists (MRAs) in managing CKD and proteinuria." (PMID 38173862, 2023). "Drugs suppressing the renin-angiotensin system or blocking aldosterone receptors are linked with hyperkalaemia." (PMID 35592808, 2022). "As early as P8, animals with germline inactivation of MR, as shown in the homozygous global MR KO, suffer from hyperkalemia, hyponatremia, weight loss, and a strong increase in renin, angiotensin II, and aldosterone plasma concentrations." (PMID 35281733, 2022). "The meta-analysis showed that combination therapy of direct renin inhibitors was associated with an increased risk of moderate hyperkalemia." (PMID 36204481, 2022). "Diabetic patients, especially those with associated CKD, are more susceptible to present potassium disorders, in particular hyperkalemia due to kidney disease progression or use of renin-angiotensin-aldosterone blockers." (PMID 35466190, 2022). "Hyperkalemia is associated with many chronic diseases and renin-angiotensin-aldosterone system inhibitor therapy." (PMID 33098526, 2021). "Treatment with antihypertensive agents, ACE inhibitors, angiotensin receptor blockers (ARBs), a direct renin inhibitor, and MR blockers are all known to increase the risk of hyperkalemia." (PMID 33214722, 2021). "Elderly individuals are physiologically susceptible to hyperkalemia due to an age-related decline in renin–aldosterone secretion, and this risk is further amplified in those complicated by impaired renal function." (PMID 34063969, 2021). "In patients with diabetes, multiple studies have reported that treatment with MR blockers, ARBs, ACE inhibitors, or a direct renin inhibitor is associated with an increase in potassium levels and a risk of severe hyperkalemia in a small number of patients." (PMID 33214722, 2021). "Three patients had MC deficiency (P1 and P3 had mild hyponatremia and high plasma renin activity, P2 presented with severe hyponatremia and hyperkalemia), and needed FC at a dose of 0.05 mg/day, orally." (PMID 32938577, 2021). "The combination of a direct renin inhibitor with other RAAS inhibitors also significantly increased the risk of hyperkalemia." (PMID 30909873, 2019). "Esaxerenone showed antihypertensive and antialbuminuric effects and a low risk of hyperkalemia with dosage titration from 1.25 mg in Japanese hypertensive patients with type 2 diabetes and albuminuria receiving a renin–angiotensin system inhibitor." (PMID 31239535, 2019).
Hyperkalemia (continued). "ADTKD-REN is caused by mutations in the REN gene encoding renin and is associated with childhood anemia, hyperuricemia, gout, and hyperkalemia." (PMID 29513881, 2018). "Two of these reports indicated that the prolonged hyperkalemia was due to hypoaldosteronism caused by the zona glomerulosa function occurring as a result of suppressed plasma renin levels after surgery." (PMID 24343173, 2015). "Some clinical aspects associated are hyponatremia, hyperkalemia, and elevated plasma aldosterone and plasma renin activity." (PMID 19721811, 2009). "Because impaired neural control may cause decreased renin release and aldosteron production and neuropathic patients may have hyperkalemia." (PMID 40717832, 2025). "Renin–angiotensin system inhibitors (RASi) are a recognized risk factor for hyperkalemia in CKD; however, discontinuing RASi in response to elevated potassium levels may adversely affect patient outcomes." (PMID 40705102, 2025). "One possible explanation is that spironolactone is frequently co-administered with renin–angiotensin system inhibitors such as ACEIs or ARBs, which collectively increase the risk of hyperkalaemia and may contribute to the higher observed incidence of DDIs." (PMID 41573738, 2025). "This may be related to the increased risk of hyperkalemia caused by the dual inhibition of the renin–angiotensin–aldosterone system." (PMID 40824899, 2025). "However, dual inhibition of the renin–angiotensin–aldosterone system instantly can increase the risk of acute kidney injury and hyperkalemia, and therefore, caution is warranted." (PMID 39248389, 2024). "However, common causes of hyperkalemia result from inadequate renal potassium excretion; this can be classified into two groups—impairment of renal function and disruption of the renin-angiotensin-aldosterone system (RAAS)." (PMID 38292832, 2024). "Studies have shown that these MRAs, while beneficial for reducing cardiovascular mortality and hospitalization, increase the risk of hyperkalemia, particularly in patients with renal dysfunction or those also receiving other renin–angiotensin system inhibitors." (PMID 39541086, 2024). "The observed infrequent use of ACEIs could be associated with their risk of inducing hyperkalemia caused by blockage of the renin-angiotensin-aldosterone pathway." (PMID 38282776, 2023). "Moreover, even though the CPGs recommend against the dual blockade of the renin-angiotensin system due to excessive risk of hyperkalaemia, hypotension, and renal failure, a small percentage of our patients were on ACE inhibitor and ARB combination therapy." (PMID 37833402, 2023). "The widely used Renin-angiotensin-aldosterone systeminhibitor (RASI) may increase the risk of hyperkalemia and acute kidney injury(AKI)." (PMID 39076277, 2023). "Renin-angiotensin-aldosterone system inhibitors may occasionally be difficult to use due to a risk of hyperkalemia and a decline in the eGFR in diabetic patients with renal impairment." (PMID 37733761, 2023). "In addition, β-inhibitors and NSAIDs are prone to cause hyperkalemia by altering the distribution of K in and out of cells, and renin secretion, respectively." (PMID 34063969, 2021). "On the other hand, in patients with cardiac or renal disease, hyperkalemia is often associated with medications that suppress the renin–angiotensin–aldosterone system, such as angiotensin-converting enzyme (ACE) inhibitors, angiotensin receptor blockers (ARBs), and K-retaining diuretics." (PMID 34063969, 2021). "This could be attributed to dysautonomia in long-standing DM which impairs the conversion of prorenin to renin and predisposes to hyporeninaemic hypo-aldosteronism and associated hyperkalaemia." (PMID 32832115, 2020). "Dosing of renin–angiotensin–aldosterone system inhibitors (RAASi) may be modified to manage associated hyperkalemia risk; however, this approach could adversely affect cardiorenal outcomes." (PMID 31711387, 2019).
Hyperkalemia (continued). "Our findings are in keeping with those of a Canadian nested case-control study of older patients taking renin-angiotensin system blockers that identified a nearly sevenfold increased risk of hospital admission for hyperkalaemia with co-trimoxazole compared with other antibiotic drugs." (PMID 29438980, 2018). "The relative risk increase is similar across population groups, but the higher baseline risk among those taking renin-angiotensin system blockers and potassium-sparing diuretics translates into higher absolute risks of acute kidney injury and hyperkalaemia in these groups." (PMID 29438980, 2018). "For example, use of inhibitors of the renin-angiotensin-aldosterone system in the setting of kidney disease may have a higher risk associated with hyperkalemia and further renal impairment." (PMID 28426831, 2017). "In addition to interfering with the renin-aldosterone axis, medications can cause hyperkalemia by other mechanisms." (PMID 23882341, 2011). "Impaired renin-aldosterone axis can cause enhanced hyperkalemia." (PMID 23882341, 2011). "Impaired renin production and release due to renal tubular damage, decreased aldosterone production as a result of adrenal dysfunction, or failure of principal cells to respond normally to aldosterone may impair potassium excretion and cause hyperkalemia." (PMID 40717832, 2025). "In general, the current evidence suggests that sacubitril/valsartan does not convincingly lead to an absolute reduction in the risk of renal dysfunction and hyperkalemia, although it may result in a slower rate of decrease in eGFR compared to inhibition of the renin-angiotensin system alone." (PMID 39742017, 2024). "In addition to elevated ACTH as one of the diagnostic criteria of PAI, the elevation of the renin level and hyperkalaemia induced by adrenal insufficiency could help support the diagnosis of PAI." (PMID 35870109, 2022). "This age‐related reduction in plasma renin and aldosterone may cause hyperkalemia." (PMID 34532036, 2021). "Laboratory tests revealed severe hyponatremia, hyperkalemia, elevated plasma renin, and decreased cortisol levels." (PMID 41889508, 2026). "The diagnosis is based on the declaration of the treating physician in addition to biochemical evidence of hyponatremia, hyperkalemia, and when available, renin levels and molecular results." (PMID 41394115, 2026). "Plasma and urine aldosterone levels typically remain within the normal range due to suppressed renin activity, although hyperkalemia independently tends to stimulate aldosterone secretion." (PMID 40530196, 2025). "Reduced adrenal aldosterone production due to a blockage of the renin-aldosterone axis results in hyperkalemia." (PMID 40291321, 2025). "In cases of persistent symptoms despite corticosteroid dose adjustments, peripheral adrenal insufficiency should be considered, especially with hyperkalemia, high renin, and low aldosterone." (PMID 40860571, 2025). "The postulated theories of β-blocker-induced hyperkalemia include inhibition of renin production, disruption of intracellular potassium uptake, and promotion of endothelial cell apoptosis, which releases intracellular potassium." (PMID 40291321, 2025). "PHA-2 is more commonly seen in adults and is characterized by hypertension, hyperkalemia due to fluid overload, and variable aldosterone levels with suppressed renin, reflecting a different pathophysiology." (PMID 40648780, 2025). "Background/Objectives: Pseudohypoaldosteronism type 1 (PHA-1) is a rare disorder characterized by aldosterone resistance, leading to hyponatremia, hyperkalemia, and elevated renin and aldosterone levels in neonates and infants." (PMID 40648780, 2025). "For example, beta-adrenergic blockade reduces renin release and leads to hyperkalemia in a given patient who is usually normokalemic." (PMID 40717832, 2025).